FADD (Fas associated via death domain)
Diseases named in the same sentence as FADD in open-access papers (continued):
Sharing a sentence is not in itself a finding about the gene and the disease.
oral squamous cell carcinoma (7 papers, 2010 to 2025). "Regarding cancer, one study reported an association between significant hypermethylation of FADD promoter in oral squamous cell carcinoma and reduced FADD expression." (PMID 31569512, 2019). "According to the previous reports, high expression of FADD was associated with factors indicating poor prognosis in squamous cell carcinoma of the head and neck and oral squamous cell carcinoma." (PMID 24886289, 2014). "FADD expression was associated with metastasis in squamous cell carcinoma of the head and neck and poor prognosis in oral squamous cell carcinoma and lung adenocarcinoma." (PMID 24886289, 2014). "The positive percentage of FADD was 65.2% (15/23) and 25.0% (2/8) in oral squamous cell carcinoma tissues and oral epithelial tissues, respectively (p < 0.05)." (PMID 34423028, 2021). "Positive expression of FADD proteins was detected in the oral squamous cell carcinoma and laryngeal carcinoma tissues." (PMID 34423028, 2021). "This study was designed to explore the role of FADD in oral squamous cell carcinomas (OSCCs) samples from Taiwanese patients, by assessing copy number variations (CNVs) and protein expression and the clinical implications of these factors in 339 male OSCCs." (PMID 27764170, 2016). "We detected FADD and NKX2-3 expression in oral squamous cell carcinoma cell lines HSC-3, HSC-4, and HSC-6 and human oral squamous cell line HOK by RT-qPCR." (PMID 34423028, 2021). "A similar correlation has been reported for cell lines from oral squamous cell carcinoma (TPCN2, CCND1, ORAOV1, ANO1, FADD, PPFIA1 and EMS1; FADD, PPFIA1 and EMS1)." (PMID 20664600, 2010).
skin inflammation (7 papers, 2016 to 2025). "Our genetic studies showed that epidermis-specific ablation of FADD or caspase-8 caused skin inflammation by inducing RIPK3-MLKL-dependent necroptosis of keratinocytes." (PMID 38849574, 2024). "Here we identified a critical interplay between RIPK3-MLKL-dependent necroptosis and FADD-caspase-8-mediated apoptosis that controls skin inflammation downstream of TNFR1 and ZBP1." (PMID 38849574, 2024). "Here we show that combined ablation of TNFR1 and ZBP1 fully prevented skin inflammation in FADDE-KO mice, demonstrating that ZBP1-mediated necroptosis drives TNFR1-independent skin inflammation upon keratinocyte-specific inhibition of FADD/caspase-8 signaling." (PMID 38849574, 2024). "ZBP1 induced TNFR1-independent skin inflammation in mice with epidermis-specific ablation of FADD by triggering keratinocyte necroptosis." (PMID 38849574, 2024). "The complete rescue from dermatitis upon genetic deletion of both FADD and MLKL proves that keratinocyte cell death is the driving force of the skin inflammation and tumorigenesis in ΔKerOTULIN mice." (PMID 34625556, 2021). "MLKL deficiency could ameliorate but not prevent dermatitis development in ΔKerOTULIN mice, suggesting that both FADD-dependent apoptosis and MLKL-dependent necroptosis are driving the skin lesion development in ΔKerOTULIN mice." (PMID 34625556, 2021). "Caspase-8 heterozygosity significantly delays dermatitis onset, while co-deletion of FADD (in the skin) and RIPK3 was required to entirely ablate skin inflammation, implying that inflammation is primarily driven by apoptosis, with a minor role for necroptosis." (PMID 33924766, 2021). "The observation that genetic deletion of both FADD and MLKL in keratinocytes protects ΔKerOTULIN mice from dermatitis development, proved that cell death of keratinocytes is the driving force of the cutaneous inflammation developing in ΔKerOTULIN mice." (PMID 34625556, 2021). "Moreover, the skin inflammation in these mice was driven by TNF, epithelial TNFR1 and RIPK1 kinases, FADD/ caspase-8-mediated cell death, and innate immune sensors, adaptors and components of inflammasomes." (PMID 40006996, 2025). "In conclusion, we could demonstrate that dermatitis and tumor development in ΔKerOTULIN mice depends on the cytotoxic activity of TNF driving FADD- and RIPK1 kinase-dependent death of keratinocytes." (PMID 34625556, 2021). "However, because inhibition of FADD/caspase-8 signaling in keratinocytes triggers TNFR1- and ZBP1-mediated necroptosis and skin inflammation, it is not possible to use conditional ablation of FADD or caspase-8 alone to assess the role of FADD/Caspase-8-induced signaling in ZBP1caE-het mice." (PMID 38849574, 2024).
acute lymphoblastic leukemia (6 papers, 2015 to 2022). Leukemia with an acute onset, characterized by the presence of lymphoblasts in the bone marrow and the peripheral blood. "We then investigated a regulatory role of FADD in T-acute lymphoblastic leukemia (T-ALL) using Jurkat cells as a model." (PMID 35637951, 2022). "FADD DISC assembly inhibiting the extrinsic pathway of apoptosis upon drug treatment, and thus inducing chemo-resistance in T-acute lymphoblastic leukemia cell lines." (PMID 33450869, 2021).
colorectal cancer (6 papers, 2014 to 2022). A primary or metastatic malignant neoplasm that affects the colon or rectum. "HIPK3 promotes FADD phosphorylation and metabolic reprogramming in colorectal cancer." (PMID 35096570, 2021).
Hypertension (6 papers, 2016 to 2023). The presence of chronic increased pressure in the systemic arterial system. "Considering the strong associations between hypertension, stroke, and coronary heart diseases, the findings from these studies are supportive of the role of FADD and our prediction that the inhibition of FADD expression may be associated with treatment of hypertension (or its complications)." (PMID 35213968, 2022). "Our results indicated the new finding that EGCG treatment was able to prevent the early aged hypertension-activated Fas-mediated Caspase-dependent neural apoptotic pathway, as evidenced by the down-regulated levels of FasL, Fas, FADD, Caspase-8, and Caspase-3 in the hypertensive cerebral cortex." (PMID 34456710, 2021). "Our present study demonstrated that exercise training played a significant role in inhibiting hypertension-induced Fas/FasL-mediated caspase-dependent apoptotic pathway in the cerebral cortex, as indicated by decreased expression levels of FasL, Fas, FADD, active Caspase-8, and active Caspase-3." (PMID 34432648, 2021). "In order to determine the EGCG effects on the upstream components of neural Fas receptor Caspase-dependent apoptotic pathway in early aged hypertension, we evaluated the protein expressions of FasL, Fas, and FADD in the cerebral cortex tissues from the WKY, SHR, and SHR-EGCG groups." (PMID 34456710, 2021). "In the regulation of apoptosis, exercise training downregulated the proapoptotic protein in hypertension by decreasing the upstream regulation of apoptosis such as the Fas ligand, TNF, TNF receptor 1, and FADD, and the downstream regulation of apoptosis such as t-Bid, Bad, Bak, and Bax." (PMID 37187789, 2023).
ileitis (6 papers, 2020 to 2025). "Upstream, loss of ZBP1 is sufficient to prevent ileitis in both mice with caspase-8- and FADD-deficient IECs." (PMID 35563804, 2022). "Similarly, MLKL deficiency inhibited ileitis caused by the removal of epithelial caspase-8 but only marginally mitigated ileitis in mice deficient in FADD in IECs, implying that MLKL promotes necroptosis or that its deficiency prevents necroptosis." (PMID 39118979, 2024). "Colitis and ileitis also occur in mice lacking FADD in IECs, with cell death mediated by MLKL and caspase-8-dependent activation of GSDMD." (PMID 35563804, 2022).
lymphoma (6 papers, 2007 to 2022). A malignant (clonal) proliferation of B- lymphocytes or T- lymphocytes which involves the lymph nodes, bone marrow and/or extranodal sites. "Interestingly, loss of BID, together with FADD (Fas associated via death domain) and TRAIL (tumor necrosis factor-related apoptosis-inducing ligand), was reported to contribute to resistance of lymphoma cells to CD19 CAR T-cells." (PMID 34868059, 2021).
cervical carcinoma (5 papers, 2013 to 2019). A carcinoma arising from either the exocervical squamous epithelium or the endocervical glandular epithelium. "According to the information collected by The Human Protein Atlas, the FADD level is an unfavorable prognostic marker in lung, head and neck, and cervical cancers, whereas it constitutes a favorable prognostic marker in thyroid cancer." (PMID 31569512, 2019). "Cervical cancer cells treated with hesperetin (flavonoid from citrus fruits) displayed an upregulated Fas death receptor and its adaptor protein FADD." (PMID 23773282, 2013). "Inhibiting E6 interactions with FADD could provide a promising treatment for cervical cancer." (PMID 31387520, 2019). "Deletions and LOH encompassing FADD gene within 11q13 have been found in 25% (9/36) of cervical cancer samples, although FADD was not identified as a driver of the potential LOH-derived tumorigenic effects." (PMID 31569512, 2019).
gastric cancer (5 papers, 2017 to 2022). A primary or metastatic malignant neoplasm involving the stomach. "In our previous work, we showed that high miR-633 expression was closely associated with FADD loss in gastric cancer (GC) tissue and cell lines." (PMID 36348274, 2022). "A recent paper has shown that H19 and miR-675 increase in gastric cancer, and overexpression of H19 and miR-675 promotes cell proliferation and inhibits apoptosis by downregulation of FADD." (PMID 33499244, 2021).
laryngeal carcinoma (5 papers, 2008 to 2021). Carcinoma that arises from the laryngeal epithelium. "In this paper, we compared, using immunohistochemical analysis for cyclin D1, FADD and cortactin in a series of 106 laryngeal carcinomas which gene correlates best with lymph node metastases and increased disease-specific mortality." (PMID 18268491, 2008). "Laryngeal cancer patients with high FADD expression exhibited a high mortality rate." (PMID 34093817, 2021). "Also, approximately 66.7% (14/21) of laryngeal carcinoma tissues and 28.6% (2/7) of laryngeal epithelial tissues were positive for FADD." (PMID 34423028, 2021). "Furthermore, FADD protein expression correlated with disease specific mortality (DSM) in a series of late stage laryngeal carcinomas." (PMID 18268491, 2008). "This suggests that EGFR and INHBA can serve as prognostic hub genes for laryngeal cancer collectively with pRS genes (CFLAR, DAPK2, TSC2, CAPN10, MBTPS2, PEX14, FADD and ST13)." (PMID 34093817, 2021). "On the contrary, another group reported that phosphorylated FADD was not prognostic in laryngeal carcinoma treated with radiotherapy, confirming that the predictive value of phosphorylated FADD also depends on cellular type and context." (PMID 31569512, 2019).
liver cancer (5 papers, 2019 to 2024). An epithelial or non-epithelial malignant neoplasm that arises from the liver. "Suillin, extracted from the mushroom Suillus placidus, upregulated both death receptor Fas and its adaptor, Fas-associated death domain protein (FADD), with the resultant caspase 8 inducing apoptosis in HepG2 liver cancer cells." (PMID 33669877, 2021). "In liver cancer, miR-675 is upregulated along with the overexpression of H19, which suppresses FADD." (PMID 38355574, 2024). "FADD is inhibited in HCC, and its reduced expression inhibits its role in mediating liver cancer cell apoptosis." (PMID 38321105, 2024). "Specifically, dehydrocrenatidine significantly increased the expression of extrinsic pathway components (FAS, DR5, FADD, and TRADD) as well as intrinsic pathway components (Bax and Bim L/S) in liver cancer cells." (PMID 35455398, 2022). "Genes with 5-mC and 5-hmC level changes enriched in these pathways, such as BMP4, HSP90AA1, DAPK3, FADD and CASP8, have been already reported as potential epigenetic biomarkers for liver cancer." (PMID 31337442, 2019).
myeloma (5 papers, 2007 to 2024). "Defect in the death receptor signally caused by impaired FADD/BID expression leads to failure of T-cell mediated immunotherapy in multiple myeloma patients." (PMID 38129580, 2023). "An examination of the relative expression levels of FADD, caspase-8, RIP1, and RIP3 in the lenalidomide- and bortezomib-resistant myeloma cells and their parental myeloma cells might help identify a possible programmed cell death pathway to overcome drug resistance." (PMID 35321428, 2022).
myocardial ischemia (5 papers, 2017 to 2025). A disorder of cardiac function caused by insufficient blood flow to the muscle tissue of the heart. "MiR-103/107 regulate programmed necrosis and myocardial ischemia/reperfusion injury via targeting FADD (Fas-associated protein with death domain)." (PMID 30717412, 2019). "Our data demonstrate that AKT2 inhibition induces the silencing of caspase activation which mediates both FADD (Fas-associated death domain)- and mitochondrial-dependent apoptosis during cardiac ischemia." (PMID 28272306, 2017). "MicroRNA-103/107 regulates programmed necrosis and myocardial ischemia/reperfusion injury by targeting FADD." (PMID 30743213, 2019).
squamous cell carcinoma (5 papers, 2016 to 2024). A carcinoma arising from squamous epithelial cells. "FADD overexpression occurs frequently in squamous cell carcinoma of the head and neck, and is associated with metastasis." (PMID 29051715, 2017). "Consistent with previous studies, FADD gene copy number variation and protein expression are potential prognostic markers for squamous cell carcinoma of the head and neck." (PMID 34093817, 2021). "We also showed that FADD contributed to unfavorable overall survival and immune infiltration of HNSCC, suggesting that FADD might be a crucial oncogene in squamous cell carcinoma." (PMID 38684755, 2024).
Stroke (5 papers, 2014 to 2025). Sudden impairment of blood flow to a part of the brain due to occlusion or rupture of an artery to the brain. "Following stroke, pro-inflammatory cytokines including TNF-α and IL-1β activate the Fas/FasL system, recruiting Fas-associated death domain (FADD) protein and procaspase-8." (PMID 41451361, 2025). "Flowchart illustrating the protective effect of zinc on stroke through various stages: GWAS analysis and NHANEs database, bioinformatic analysis, diagnostic model, pathway analysis showing autophagy, and genes involved (RELA, TNFSF10, NFE2L2, FADD, DDIT3, CFLAR)." (PMID 40969765, 2025). "In addition, Apaf-1 (apoptotic associated factor 1), FADD (Fas (TNFRSF6)-associated via death domain) and Bcl-2, up regulated in female cardioembolic stroke, have all been associated with female cell death following stroke." (PMID 25036109, 2014). "The key genes encompass critical pathways such as autophagy (e.g. NFE2L2, DDIT3, NAMPT), apoptosis (e.g. CFLAR, FADD) and NF-κB signaling (e.g. RELA, TNFSF10), suggesting a multifactorial involvement of these pathways in stroke pathophysiology." (PMID 40969765, 2025).
Yersinia infection (5 papers, 2022 to 2025). "Importantly, FADD-/- cells also undergo significantly less cell death following LPS+IKKi treatment and significantly less caspase-3/7 activation following Yersinia infection." (PMID 39186805, 2024). "Recently, Yersinia infection was found to activate PANoptosis, with infection inducing the formation of a PANoptosome containing RIPK1, RIPK3, caspase-8, ASC, FADD, and NLRP3." (PMID 35563804, 2022). "PANoptosomes have also been identified by immunoprecipitation during Yersinia infection, where RIPK1, RIPK3, caspase-8, FADD, ASC, and NLRP3 can be co-immunoprecipitated." (PMID 35563804, 2022).
atherosclerosis (4 papers, 2018 to 2024). A disease characterized by the build-up of fatty material and calcium deposition in the arterial wall resulting in partial or complete occlusion of the arterial lumen. "Another target of interest is FADD, which is also a marker of apoptosis and apoptosis that may be implicated in atherosclerosis." (PMID 35213968, 2022). "MiRNA 103 is believed to play a role in cardiomyocyte necrosis and atherosclerosis through activation of FADD and by suppression of KLF4." (PMID 37438691, 2023). "To further study whether FGF21 inhibits atherosclerosis via ameliorating Fas-mediated apoptosis in apoE−/− mice, we measured the mRNA and protein expression of Fas and FADD in the apoE−/− mice and apoE−/− mice treated with FGF21." (PMID 30157856, 2018). "We found that the protective effect of FGF21 against atherosclerosis might be due to its inhibitory effects on Fas/FADD-mediated apoptosis." (PMID 30157856, 2018). "We speculate that FGF21 prevents atherosclerosis through a mechanism that involves reducing Fas/FADD-mediated apoptosis in endothelial cells." (PMID 30157856, 2018). "FGF21 inhibited atherosclerosis through mitigating Fas-mediated apoptosis in ApoE-/- mice, and in vitro studies have found that FGF21 inhibited apoptosis and prevented atherosclerosis progression in HUVEC through the Fas/FADD mechanism." (PMID 39558976, 2024).
diabetes (4 papers, 2007 to 2022). "FADD is located on chromosome 11q13.3, a diabetes susceptibility locus; therefore, it has been suspected that alterations in FADD might result in diabetes." (PMID 27357657, 2016). "Blocking multiple TNFR molecules increases diabetes protection, for example, by overexpression in islets of dominant negative FADD, the adaptor protein used by multiple death receptors to recruit and activate caspase-8." (PMID 17254331, 2007).
osteosarcoma (4 papers, 2019 to 2026). A usually aggressive malignant bone-forming mesenchymal neoplasm, predominantly affecting adolescents and young adults. "In the present study, we report that AS1842856-mediated inhibition of FOXO1 reverses anticancer drug-induced cytotoxicity, while FADD knockdown increases anticancer drug-induced cytotoxicity in osteosarcoma (OS)." (PMID 41596582, 2026). "Non-apoptotic functions for FADD in osteosarcoma (OS) have not been reported." (PMID 32194778, 2020).
pharyngeal cancer (4 papers, 2014 to 2022). "This chromosome region contains several genes that are potentially cancer drivers, including FADD (Fas associated via death domain), an apoptotic effector that was previously identified as a novel oncogene in laryngeal/pharyngeal cancer." (PMID 27764170, 2016). "FADD, which is also located within 11q13.3, was previously identified as a novel cancer gene in laryngeal/pharyngeal cancer." (PMID 27764170, 2016). "FADD amplification has been demonstrated to play a role in laryngeal/pharyngeal cancer, and high protein expression (43%) was shown to be associated with worse survival in patients with tongue cancer." (PMID 27764170, 2016). "FADD, an apoptotic effector molecule, was previously identified as a novel cancer driver gene in a panel of 167 laryngeal/pharyngeal cancers, warranting further investigation into its mechanism of oncogenesis." (PMID 24874471, 2014). "However, high FADD expression was also observed in multiple cancer types, including pancreatic cancer (PC), laryngeal/pharyngeal cancer, OSCC, HNSCC, and BC." (PMID 36348274, 2022). "Expression of FADD and RIPK1 in different groups of hypo pharyngeal carcinoma." (PMID 34262870, 2021).
asthma (3 papers, 2021 to 2025). "Taken together, these results showed that the exacerbated lung inflammation in HDM-challenged FADDAEC-KO mice is specifically linked to the loss of FADD in AECs and depends on RIPK3, suggesting that increased necroptosis of FADD-deficient AECs contributes to the worsening of HDM-induced asthma." (PMID 34045680, 2021). "Whereas FADD ablation in AECs did not disturb normal lung homeostasis under steady-state conditions, it caused exacerbated asthma-like lung pathology in response to HDM sensitization and challenge." (PMID 34045680, 2021). "In contrast, the pathways enriched in the low FADD subtype were primary immune defense, ABC transport, and asthma." (PMID 37671047, 2023). "Lack of RIPK1 kinase activity or RIPK3 or MLKL deficiency did not protect mice with intact FADD signaling from HDM-induced airway inflammation, showing that RIPK1-RIPK3-MLKL-mediated necroptosis does not play an important role in HDM-induced asthma in wild type mice." (PMID 34045680, 2021).